SCN4A (sodium voltage-gated channel alpha subunit 4)
Diseases named in the same sentence as SCN4A in open-access papers (continued):
Sharing a sentence is not in itself a finding about the gene and the disease.
neuromuscular disease (4 papers, 2021 to 2024). "Non-dystrophic myotonias (NDM) are rare hereditary neuromuscular diseases caused predominantly by mutations in CLCN1 or SCN4A, respectively coding for the voltage-gated muscle channels ClC-1 and NaV1.4." (PMID 33263785, 2021).
tumor (4 papers, 2021 to 2024). "According to the results, SCN4A/5A/8A were highly expressed in tumour tissues, while SCN1A/2A/7A/11A were expressed at low levels (p < 0.05)." (PMID 35126466, 2021). "The pan-tumour analysis showed that SCN7A expression was stably lower in tumours than SCN4A expression by TIMER." (PMID 35126466, 2021). "The mRNA expression level of SCN4A/7A was also significantly related to individual tumour stages; similarly, SCN4A was highly expressed in every stage, but SCN7A expression decreased in stage 3 and stage 4." (PMID 35126466, 2021). "Next, we performed a pan-tumour analysis of SCN4A and SCN7A in the TIMER database." (PMID 35126466, 2021). "The results showed that ANXA5, MMP1, MTR, REN, SCN4A, and SMAD3 were upregulated in HC samples, while HP and ACOX1 were downregulated in tumor tissues." (PMID 38599581, 2024). "In the TCGA-HNSC cohort, we observed the expression of 12 ion channel genes in tumor and normal tissues; ANO1, AQP9, BEST2, CHRNA5, and KCNJ15 were upregulated in HNSCC, while AQP1, AQP5, SCNN1G, and SCN4A were downregulated." (PMID 36389709, 2022). "The findings revealed that ANO1, AQP9, and BEST2 were upregulated in tumor tissues, and AQP5, SCN4A, and SCNN1G expression was upregulated in normal tissue from 12 HNSCC patients." (PMID 36389709, 2022). "The mRNA expression of SCN4A was significantly higher at every grade, and the expression of SCN7A gradually decreased with the increase in tumour grade, but only significantly changed in grade 1 and grade 3." (PMID 35126466, 2021). "Our analysis identified seven tumour suppressor genes (ITGA7, SLC45A1, TPPP, SCN4A, GIPR, SOGA3 and RAB6B) and six oncogenes (SAT1, SERPINE1, UPK2, SYT12, RASAL1 and CDH3) with significant false discovery rate (FDR)-adjusted P values (q-value) of less than 0.05." (PMID 38429478, 2024). "The results of the UALCAN database had showed that SCN2A/4A/5A/8A mRNA were highly expressed in tumour tissues, while SCN1A/7A/11A mRNA were expressed at low levels (p < 0.05), furthermore, the expression of SCN4A and SCN7A had the similar levels in microarray analysis result." (PMID 35126466, 2021). "Additionally, the expression of SCN4A was higher in tumours, while that of SCN7A was lower, suggesting that SCN4A and SCN7A might have different effects in HCC." (PMID 35126466, 2021).
peripheral neuropathy (3 papers, 2016 to 2021). A disorder affecting the peripheral nervous system. "Gene alterations, such as GSTP1 and GSTM1, glutathione-S-transferase genes and voltage-gated sodium channel genes SCN4A, SCN9A and SCN10A, together with pre-existing peripheral neuropathy have been demonstrated to be the principal risk factors for OIPN onset." (PMID 33671327, 2021).
autosomal dominant disease (1 paper, 2025). Autosomal dominant form of disease. "PMC is an autosomal dominant disease caused by point mutations in the SCN4A gene on chromosome 17q, which encodes for the alpha subunit of the voltage-gated sodium channel in skeletal muscles, known as Nav1.4." (PMID 41164065, 2025).
SCN4A also shares sentences with these, for which no sentence is quoted: congenital myasthenic syndrome (19 papers); potassium-aggravated myotonia (6); myotonic syndrome (5); Andersen-Tawil syndrome (4); hypokalemic periodic paralysis, type 2 (4); muscle disorders (3); myasthenia (3); ovarian carcinoma (3); Arrhythmia (2); Bradycardia (2); cervical cancer (2); congenital myasthenic syndrome type 16 (2); Laryngospasm (2); long QT syndrome type 3 (2); neurodegenerative disease (2); neurological diseases (2); neuropathies (2); prostate carcinoma (2); Apnea (1); arthrogryposis (1); atherosclerosis (1); atrial fibrillation (1); atrioventricular block (1); Cachexia (1); cardiac arrest (1); cardiovascular diseases (1); developmental epileptic encephalopathy (1); dilated cardiomyopathy (1); Duchenne muscular dystrophy (1); encephalopathies (1).
A further 35 diseases each share a sentence with SCN4A in 1 paper.